MIR3170 (microRNA 3170)
Synonyms: hsa-mir-3170; mir-3170
Gene: MicroRNA gene on chromosome 13 (98,208,524 to 98,208,600, forward strand). Ensembl gene ENSG00000263399.
Homologues: Orthologues: chimpanzee MIR3170 (100% identical).